NQO1 (NAD(P)H quinone dehydrogenase 1)
Diseases named in the same sentence as NQO1 in open-access papers (continued):
Sharing a sentence is not in itself a finding about the gene and the disease.
ovarian carcinoma (19 papers, 2015 to 2025). A malignant neoplasm originating from the surface ovarian epithelium. "NQO1 SNP rs2917666 is a C > G variant of the NQO1 gene in the 3′ untranslated region (UTR) of the NQO1 gene, and the presence of this SNP in NQO1 gene has been significantly associated with invasive epithelial ovarian cancer." (PMID 37175546, 2023). "Univariate analysis demonstrated that histological grade (P = 0.020), FIGO stage (P = 0.000) and NQO1 expression status (P = 0.000) were all significantly associated with OS in patients with ovarian carcinoma." (PMID 25885439, 2015). "High expression of NQO1 protein was closely associated with higher histological grade, advanced clinical stage and lower OS rates in ovarian carcinomas." (PMID 25885439, 2015). "High expression of NQO1 is associated with many solid tumors including those affecting the colon, breast and pancreas; however, its role in the progression of ovarian carcinoma is largely undefined." (PMID 25885439, 2015). "Interestingly, the authors determined that the high expression of NQO1 protein was associated with higher histological grade, advanced clinical stage and lower overall survival in ovarian carcinomas." (PMID 37175546, 2023). "NRF2 and NQO1 were highly expressed in ovarian cancer and precancerous tissues compared to normal tissues, showing a positive correlation across lesion types." (PMID 41333220, 2025). "Elevated NQO1 expression in ovarian cancer has been shown to confer resistance to quinone-based chemotherapeutics and promote tumor survival, highlighting the dual role of NRF2 in cytoprotection and oncogenic adaptation." (PMID 41333220, 2025). "Daphnetin (Daph), a natural compound, was found to directly bind and inhibit NQO1, thereby increasing oxidative stress and inducing ferroptosis in ovarian cancer cells." (PMID 41333220, 2025). "In this review, we report evidence from the literature describing the effect of NQO1 on ovarian cancer onset and progression." (PMID 37175546, 2023). "We also showed a key role of NRF/KEAP1 pathway in regulating NQO1 expression in ovarian cancer cell lines." (PMID 37175546, 2023). "In this review, we discussed several studies highlighting the multifaceted role of NQO1 ovarian cancer showing that the expression or activity of this enzyme can be modulated by the presence of SNPs in its gene." (PMID 37175546, 2023). "The aim of this review is to provide an overview of the current literature regarding the role of NQO1 in ovarian cancer onset and progression with a focus on its cellular modulators and targets." (PMID 37175546, 2023). "An interesting study evaluated the role of SNPs rs1131341 and rs1800566 in NQO1 gene in patients with ovarian cancer receiving cisplatin/cyclophosphamide chemotherapy." (PMID 37175546, 2023). "Cui and colleagues reported that NQO1 protein was predominantly expressed in the cytoplasm of ovarian carcinoma cells." (PMID 37175546, 2023). "NQO1 is a promising therapeutic target in ovarian cancer since it plays a pivotal role in ovarian cancer progression and chemotherapy response." (PMID 37175546, 2023). "It has been reported that NQO1 is highly expressed in many solid tumors such as uterine cervix, endometrium, lung colon, pancreas and ovarian cancer." (PMID 37175546, 2023). "The authors determined that, with the exception of epigallocatechin gallate, all other compounds showed an inhibitory effect of ovarian cancer cell lines but induced a significant increase in NQO1 expression, cell cycle arrest and apoptosis." (PMID 37175546, 2023). "Three principal SNPs in NQO1 gene have been studied in ovarian cancer: rs1800566, rs1131341 and rs2917666." (PMID 37175546, 2023). "NQO1 has a protective effect on redox cycle, oxidative stress, and tumor formation, which is upregulated in ovarian cancer and significantly correlated with poor prognosis in patients with serous ovarian cancer." (PMID 36110943, 2022).
ovarian carcinoma (continued). "Two of the known ovarian cancer-related genes are also associated with ovarian cancer prognostic outcomes (CLIC1 and NQO1)." (PMID 34215221, 2021). "NQO1 has positive cytoplasmic expression in 76%, 60% and 65% in cervical, endometrial and ovarian carcinoma respectively." (PMID 28983331, 2015). "IHC analysis of NQO1 in ovarian carcinoma cells from 160 patients revealed predominantly cytoplasmic expression." (PMID 25885439, 2015). "Strong, positive expression of NQO1 protein was observed in 63.8% (102/160) of ovarian carcinomas, which was significantly higher than in borderline serous tumors (32.3%, 20/62) or benign serous tumors (11.3%, 6/53)." (PMID 25885439, 2015). "The strongly positive rates of NQO1 protein were significantly higher in Grade 2 (G2) (61.7%, 29/47) and Grade 3 (G3) (69.7%, 53/76) ovarian carcinomas than those in Grade 1 (G1) (27.0%, 10/37) cases (P = 0.000)." (PMID 25885439, 2015). "Our data also demonstrate that positive NQO1 expression is significantly correlated with high-grade and late-stage ovarian carcinoma." (PMID 25885439, 2015). "With respect to survival, we found that ovarian carcinoma patients exhibiting high NQO1 expression had lower OS rates compared with patients with low NQO1 expression (P < 0.01)." (PMID 25885439, 2015). "NQO1 is frequently upregulated in ovarian carcinoma, and its high expression predicts poor prognosis of patients with ovarian carcinoma." (PMID 25885439, 2015). "To evaluate the relationship between NQO1 protein and ovarian carcinoma progression, we analyzed the correlation between high NQO1 expression and clinicopathological features of ovarian carcinomas." (PMID 25885439, 2015). "To further substantiate the importance of high NQO1 expression in ovarian carcinoma progression, we analyzed the OS of 160 ovarian carcinoma patients using the Kaplan–Meier method." (PMID 25885439, 2015). "The correlation between high NQO1 expression and clinicopathological features of ovarian carcinoma was evaluated by Chi-square and Fisher’s exact test." (PMID 25885439, 2015). "For the FIGO clinical stages, the strongly positive rate of NQO1 protein was 80.9% (55/68) in the late-stage (IIB–IIIC) ovarian carcinomas, but only 40.2% (37/92) in early-stage (I–IIA) cases (P = 0.000)." (PMID 25885439, 2015). "Notably, overexpression of NQO1 reversed these effects, confirming its protective role in ovarian cancer cell survival." (PMID 41333220, 2025). "Additionally, this probe imaged the NQO1 activity in three-dimensional colorectal tumor models and metastases in a mouse model of ovarian cancer." (PMID 39120303, 2024). "Thus, clinical trials are needed to evaluate the role of these two compounds in treating ovarian cancer patients since NQO1 is more expressed in ovarian cancer tissues compared to the normal ones." (PMID 37175546, 2023). "Looking at these studies, we can conclude that the high levels of NQO1 in ovarian cancer cells play a key role in stabilizing HIF-1α under hypoxia, an important factor characterizing tumor microenvironment, favoring HIF-1α-mediated processes such as tumor angiogenesis and cancer cell proliferation." (PMID 37175546, 2023). "Thus, this study clearly showed that overexpression of p62 in cisplatin-resistant ovarian cancer cell line protects cells from oxidative damage caused by vitamin K3 activating NRF2 signaling, then increasing NQO1 expression." (PMID 37175546, 2023). "We found that Nrf2 and its target genes, including HO-1 and NQO-1, were upregulated in cisplatin-resistant ovarian cancer cells, and Nrf2, the main regulator of HO-1, was of great importance for the development of cisplatin resistance in ovarian cancer." (PMID 37371947, 2023). "Moreover, the authors confirmed that NQO1 expression was significantly higher in ovarian carcinoma compared to borderline serous tumors or benign serous tumors." (PMID 37175546, 2023).
ovarian carcinoma (continued). "To identify new compounds that can efficiently change the transcriptional activity of Nrf2 protein, we engineered A2780 ovarian cancer cells to express the Firefly luciferase (FLuc) reporter gene under an ARE response element derived from NQO1, the downstream target gene of Nrf2." (PMID 36551609, 2022). "However, the ability to scavenge free radicals did not correlate with the ability of polyphenols to inhibit the growth of ovarian cancer cells or the ability to induce NQO1 expression." (PMID 30186979, 2018). "NQO1 protein expression in ovarian carcinoma cells was predominantly cytoplasmic." (PMID 25885439, 2015). "Moreover, multivariate analysis indicated that NQO1 was a significant independent prognostic factor, in addition to clinical stage, in patients with ovarian carcinoma." (PMID 25885439, 2015). "Further studies are therefore necessary to verify whether NQO1 inhibitors may be of clinical benefit to patients with ovarian carcinoma." (PMID 25885439, 2015). "Moreover, survival of patients with G1 (Log-rank = 4.359, P = 0.037), G2 (Log-rank = 7.020, P = 0.008) and G3 (Log-rank = 5.978, P = 0.015) ovarian carcinoma was significantly lower in patients with tumors exhibiting high versus low NQO1 expression." (PMID 25885439, 2015). "Similarly, ovarian carcinoma patients with high NQO1 expression had decreased OS compared with those with low NQO1 expression in either early-stage cases (Log-rank = 6.527, P = 0.011) or late-stage cases (Log-rank = 4.806, P = 0.028)." (PMID 25885439, 2015). "Similarly, the rate of strongly positive NQO1 protein expression was higher in patients with G2 or G3, compared with G1 ovarian carcinomas." (PMID 25885439, 2015). "Thus, inhibition of NQO1 may be an efficient therapeutic strategy to inhibit ovarian cancer progression." (PMID 37175546, 2023). "NQO1 expression is significantly higher in ovarian carcinoma compared to normal and precancerous lesions, suggesting that NQO1 may be a therapeutic target in ovarian cancer." (PMID 37175546, 2023). "Therefore, the development of therapies targeting NQO1 in ovarian cancer could significantly improve the outcome of this disease." (PMID 37175546, 2023). "Therefore, the authors suggest that NQO1 and NRF2 may be considered therapeutic targets for ovarian cancer care and possible early diagnostic biomarkers." (PMID 35453348, 2022). "More importantly, we observed a significant difference in the rates of positive and strongly positive NQO1 expression between borderline serous tumors and benign serous tumors (P < 0.05), indicating that NQO1 may play an important role in the progression of ovarian carcinoma." (PMID 25885439, 2015). "Although all these variants have been detected in both cancer and control samples, the authors did not report a significant prevalence of these SNPs in patients with ovarian cancer, suggesting that these variations of NQO1 may not be linked to ovarian cancer development." (PMID 37175546, 2023). "Thus, it is possible that NQO1 and XOR influence each other, suggesting that NQO1 may act on not only the prognosis of ovarian cancer, but also the cardiovascular burden associated with ovarian cancer." (PMID 37175546, 2023). "It is clear that NQO1 and NRF2 are highly expressed in ovarian carcinoma compared with normal tissues and that NRF2 expression increases with ovarian carcinoma stage advancing." (PMID 35453348, 2022). "However, to date, the role of NQO1 in ovarian carcinoma progression remains unclear." (PMID 25885439, 2015). "Moreover, factors such as NADPH: quinone oxidoreductase 1 (NQO1) and Solute Carrier Family 7 Member 11 (SLC7A11, also known as xCT) increase the antioxidant defense of ovarian cancer cells, which is the primary reason for increased chemoresistance." (PMID 39710372, 2024).
ovarian carcinoma (continued). "Interestingly, although there was an activation of NQO1 and other antioxidant enzymes such as SOD, GSTP1 and HO-1, in ovarian cancer cells treated with these compounds this antioxidant response was not sufficient to avoid cell death." (PMID 37175546, 2023). "Thus, this study demonstrates that NQO1 plays a key role in HIF-1α stabilization, and a dual treatment with dicoumarol and sorafenib can significatively increase sorafenib sensitivity in ovarian cancer cells." (PMID 37175546, 2023). "Interestingly, knockdown of lncRNA H19 in A2780/CDDP cells restored cisplatin sensitivity reducing NQO1 and NRF2 expression, proving that lncRNA H19 has a pivotal role in cisplatin resistance of ovarian cancer cells modulating NRF2/NQO1 signaling." (PMID 37175546, 2023). "This expression pattern of NQO1 and NRF2 was also reported by Bao and colleagues, who detected an increased expression of NQO1 and its regulator NRF2 in cisplatin-resistant ovarian cancer cells A2780/CDDP compared to cisplatin-sensitive parental cell line A2780." (PMID 37175546, 2023). "Interestingly, both NQO1 and NRF2 are highly expressed in ovarian carcinoma compared to normal and precancerous lesions, showing a positive correlation in the different lesions." (PMID 35453348, 2022). "Treatment with polyphenols at physiological doses did not significantly alter the growth of ovarian cancer cells or NQO1 expression." (PMID 30186979, 2018). "We found that high expression of NQO1 (HR: 1.796, 95% CI: 1.250–2.580, P = 0.002) and FIGO stage (HR: 1.736, 95% CI: 1.228–2.453, P = 0.002) were significant independent prognostic factors for survival in ovarian carcinoma." (PMID 25885439, 2015). "Although there are not clinical trials evaluating NQO1 modulation in ovarian cancer, two interesting clinical trials showed important results regarding the use of two compounds that can exploit the high expression of NQO1 in tumor cells compared to normal cells." (PMID 37175546, 2023). "However, to date, the role of NQO1 as a biomarker in ovarian carcinoma progression has not been elucidated." (PMID 25885439, 2015). "However, high expression of NQO1 protein was not related with age, menopausal status of patients with ovarian carcinoma." (PMID 25885439, 2015).
Nephropathy (17 papers, 2008 to 2025). A nonspecific term referring to disease or damage of the kidneys. "This, together with the fact that inhibition of NQO1 is linked to the amelioration of kidney diseases, enables a new discovery, namely the relation between isopropanol and kidney diseases." (PMID 35070506, 2022). "We found that both NFE2L1 and NQO1 expressions were significantly diminished across all observed renal diseases." (PMID 37681897, 2023). "In particular, the expression of the pro-fibrotic markers, Smad3, α-SMA, and collagen, was especially enhanced in STZ-treated Nqo1 KO mice, implying the progress of interstitial fibrosis implying leading to end-stage kidney disease." (PMID 33672316, 2021). "Microarray analysis and AAI-treated mouse models showed that GNMT moderately reduced AAI-induced nephropathy by lowering the upregulated level of NQO1 in male, but significantly improved the nephropathy additionally by increasing Cyp3A44/3A41 in female." (PMID 29725048, 2018). "Nrf2 signalling regulates expression of many genes that oppose inflammatory and oxidative damage, including HO‐1, SODs, and NQO1, which is protective in various models of renal disease." (PMID 30320493, 2018). "In a mouse model of ischemia-reperfusion injury- (IRI-) induced kidney damage, the maximal response of NQO1 mRNA to IRI was an ~1.8-fold increase in wild-type mice and a 5-fold increase in KEAP1-knockdown mice." (PMID 28785379, 2017). "It was also found that EN patients homozygous for the NQO1*2 allele were at increased risk of developing UTT (OR 13.75), suggesting the importance of NQO1 in AA activation and development of nephropathy." (PMID 22069645, 2010). "In this study, PA and EPI reduced ROS and MDA levels and increased GSH‐Px, T‐SOD, Nrf2, HO‐1, and NQO‐1 levels, suggesting that EPI can inhibit the oxidative stress response in adriamycin‐induced nephropathy." (PMID 37382268, 2023). "Our study shows that PSCP treatment can improve the protein levels of Nrf2, HO-1, NQO1, and GCLM in HFD-induced kidney damage." (PMID 35223948, 2022). "In summary, hepatic GNMT protected mice from AAI nephropathy by enhancing CAR/PXR/CYP3A44/3A41 transcriptions and reducing Nrf2/NQO1 transcriptions." (PMID 29725048, 2018). "Why did we choose NQO1 and in particular the NQO1 gene expression as a readout parameter for NRF2 pathway activity and activation in kidney disease?" (PMID 28785379, 2017). "Interestingly, similar results showed that in other renal disease models, such as ischemia–reperfusion injury (IRI) and cisplatin-induced acute renal injury, NQO1 blocks renal tubular cell apoptosis and improves renal function." (PMID 35090502, 2022). "Second, reduced expression of NQO1 was shown in several kidney disease models, also in nonrenal cells, and upregulation of NQO1 was repeatedly shown in NRF2-dependent kidney protection, again including nonrenal cells." (PMID 28785379, 2017). "It is also not surprising that enhancement of antioxidants such as NQO1, catalase, and the SODs are protective in renal disease." (PMID 27804998, 2016). "In animal models of renal diseases, impaired activity of the NRF2 pathway and downregulation of the NQO1 gene expression are major findings, both in renal and in nonrenal cells." (PMID 28785379, 2017).